IFNL3 (interferon lambda 3)
Diseases named in the same sentence as IFNL3 in open-access papers (continued):
Sharing a sentence is not in itself a finding about the gene and the disease.
steatosis (20 papers, 2012 to 2018). Increased lipid within the cytoplasm of cells. "Our study revealed a clear correlation between the homozygous IFNL3 SNPs rs12979860CC, elevated cholesterol concentrations and a lower prevalence of steatosis, which is in line with previous reports." (PMID 24204859, 2013). "Additionally, APRI and steatosis were associated with the adiponectin level; age, HCV, and IFNL3 genotypes, the platelet count and the HOMA-IR score were associated with PAI-1 level." (PMID 28574439, 2017). "However, the trend was weaker in a multivariate model (OR = 1.35, 95% CI 0.91–2.01, P = 0.14), after adjustment for IFNL3 rs12979860 (P = 0.08), age at infection (P = 0.008) and steatosis (P<0.001)." (PMID 25191700, 2014). "Interaction between the IFNL3 and PNPLA3 genotypes in the pathogenesis of steatosis." (PMID 28797039, 2017).
fibrosis (17 papers, 2012 to 2021). the formation of excess fibrous connective tissue in an organ or tissue in a reparative or reactive process. "Based on previous reports linking IFNL3/IFNL4 genotypes and fibrosis risk and our current results on association with cirrhosis risk in HCV patients, we explored molecular mechanisms that could explain these associations." (PMID 34497603, 2021). "Regarding the initial METAVIR scale scores, liver transaminase levels were lower in patients with advanced fibrosis when correlated with TLR3 and IFNL3 gene expressions." (PMID 34207750, 2021). "A single nucleotide polymorphism (rs12979860) upstream of the interferon lambda 3 gene (IFNL3, IL28B) has been shown to predict post-transplant fibrosis and fibrosing cholestatic hepatitis in the absence of treatment." (PMID 27875564, 2016). "There were fewer patients of male gender and non-TT IFNL3 genotype in the advanced fibrosis group than in the mild-moderate fibrosis group, but the differences were marginal." (PMID 26334270, 2015).
Hepatitis (16 papers, 2012 to 2023). Inflammation of the liver. "The relationship between zinc and hepatitis was previously observed but associated with HCV infection, showing that zinc naturally inhibits the inflammatory and antiviral effects of interferon lambda 3 (IFN-λ3), a protein strongly associated with tissue damage in chronic liver disease." (PMID 33481813, 2021).
COVID-19 (14 papers, 2020 to 2025). A disease caused by infection with severe acute respiratory syndrome coronavirus 2. "Therefore, the aim of this study was to evaluate the impact of interferon lambda 3 and 4 (IFNL3/4) gene polymorphisms and clinical parameters on the resistance and susceptibility to coronavirus disease 2019 (COVID-19) infection." (PMID 34775984, 2021). "Methods: 141 COVID-19 positive patients and 100 healthy controls were tested for interferon-lambda-3 rs12979860, TLL1 rs17047200 and DDR1 rs4618569 polymorphism by TaqMan probe-based genotyping." (PMID 34071309, 2021). "It was interesting to observe that IFNL3 remained at elevated levels for up to 3–6 months, even in those patients with very mild COVID-19." (PMID 38953458, 2024). "IFNL3 was induced in 95% of COVID-19 patients and at higher median levels compared to the IFNL1 or IFNL2." (PMID 38953458, 2024). "IFNL3 plasma levels were also found at highest frequency and median levels in the smaller cohort of UK COVID-19 patients." (PMID 38953458, 2024). "Although ribavirin pharmacogenomics was not investigated in this study, we find it appropriate to discuss an important PGx variant IL28B (IFNL3) rs12979860, implicated in therapeutic response of ribavirin used for treating COVID-19." (PMID 33312066, 2020). "The median amount of IFNL3 was highest for patients with COVID-19." (PMID 38953458, 2024). "We next stratified data from the Irish patient cohort to investigate if IFNL3 cytokine levels could predict prognosis within hospitalized COVID-19 patients (n = 399)." (PMID 38953458, 2024). "In this study, we measured all three IFNL1, IFNL2, and IFNL3 cytokines in plasma from a well characterized, large COVID-19 cohort (n = 399) that included good representation from patients with a more indolent disease progression, and hence a beneficial immune response." (PMID 38953458, 2024). "Indeed, we found qualitative and quantitative differences in terms of frequency of induction, amount of cytokine produced and associations with severe COVID-19 outcome among IFNL1, IFNL2, and IFNL3." (PMID 38953458, 2024). "While only IFNL3 had significantly higher levels of cytokine compared to HCV + patients, both IFNL1 and IFNL2 were significantly higher in COVID-19 patients compared to healthy controls." (PMID 38953458, 2024). "From the identification of actionable pharmacogenomic markers (such as IFNL3 and SLCO1B1) to the AI-driven proposal of baricitinib as a COVID-19 therapy, we now stand at the threshold of a more systematic, integrative, and evidence-responsive approach to therapeutic innovation." (PMID 41304894, 2025). "These variations in IFNL3 and IFNL4 may have an impact on the efficacy of these drugs in COVID-19 treatment." (PMID 34306260, 2021). "In Iran, no study has evaluated the impact of SNPs on IFNL3/4 gene in COVID-19 patients." (PMID 34775984, 2021). "Our results suggest that the polymorphic status of IFNL3/IFNL4 does not affect the rate of infection, since the genotypes are fully in Hardy-Weinberg equilibrium, nor the likelihood of a severe outcome of COVID-19." (PMID 34249902, 2021).
Hepatic steatosis (11 papers, 2012 to 2022). Steatosis is a term used to denote lipid accumulation within hepatocytes. "Additionally, polymorphisms in MBOAT7 and IFNL3/4 have been shown to be associated with hepatic steatosis and necroinflammation." (PMID 32841307, 2020). "The IFNL3 genotype, pre-therapy BMI, TC, and C4 were associated with pre-therapy C3 levels, whereas post-therapy BMI, ALT, TC, WBC count, C4, and hepatic steatosis were associated with post-therapy C3 levels." (PMID 27870883, 2016). "Multivariable logistic regression analysis of factors associated with hepatic steatosis stratified by body mass index without IFNL3 SNPs taken into consideration." (PMID 28797039, 2017).
chronic hepatitis B (10 papers, 2012 to 2021). "In contrast, it has yet to be firmly established whether, and to what extent, host IFNL3 genotype might influence the response to IFN-based therapy in patients with chronic hepatitis B (CHB)." (PMID 30016335, 2018). "IFNL3 polymorphisms were associated with spontaneous resolution of HCV infection in the general population and in HD subjects as well as IFN-related HBsAg seroclearance in chronic hepatitis B patients." (PMID 28525983, 2017).
Obesity (9 papers, 2013 to 2026). Accumulation of substantial excess body fat. "We found significant associations of five highly linked SNPs of IFNL3 (rs12971396, rs8099917, rs11882871, rs12979860, rs4803217) with dyslipidemia in the population with obesity." (PMID 35784542, 2022). "We discovered the polymorphisms of IFNL3 (IL28B), an inflammation-related gene, to be associated with dyslipidemia in a population with obesity in China." (PMID 35784542, 2022). "To further adjust the effects of glucose metabolism and liver function, we undertook logistic regression analysis and confirmed that polymorphisms of IFNL3 rs12971396 (as a representative locus) were associated with dyslipidemia in people with obesity." (PMID 35784542, 2022). "We found IFNL3 (IL28B) polymorphisms to be associated with dyslipidemia in a population with obesity in China." (PMID 35784542, 2022). "There were significant differences in the allelic and genotype frequencies of IFNL3 (IL28B) rs12971396, rs8099917, rs11882871, rs12979860, rs4803217 between non-dyslipidemia and dyslipidemia groups in people with obesity." (PMID 35784542, 2022).
Insulin resistance (8 papers, 2011 to 2020). Increased resistance towards insulin, that is, diminished effectiveness of insulin in reducing blood glucose levels. "The IFNL3 genotype is associated with both insulin resistance and HS, which could partly explain the associations among the IFNL3 genotype, HS, and SVR." (PMID 28797039, 2017). "At baseline, sex, alanine aminotransferase (ALT), triglycerides, homeostatic model assessment of insulin resistance (HOMA-IR), estimated glomerular filtration rate (eGFR), hemoglobin, iron/total iron-binding capacity (Fe/TIBC) and IFNL3-rs12979860 genotypes were associated with ferritin levels." (PMID 33184464, 2020). "Also, the IFNL3 rs12979860 CC genotype has been found to be strongly associated with sustained virological response (SVR) in patients who undergo pegylated interferon plus ribavirin combination therapy, while HS and insulin resistance have also been demonstrated to be associated with SVR." (PMID 28797039, 2017).
liver cirrhosis (7 papers, 2013 to 2023). "Conversely, the role of IFNL3-gene-polymorphisms in liver cirrhosis was disputed by other investigators." (PMID 37928048, 2023). "Furthermore, research has approved the relationship between T alleles and/or T SNP of the IFNL3 gene with an increased risk of liver cirrhosis and subsequently with a higher probability of developing HCC." (PMID 37928048, 2023). "HCV genotype, BMI, liver cirrhosis and IFNL3 genotype were associated with SVR." (PMID 28211910, 2017). "Additionally, the genotypes CT and TT of IFNL3-gene were highly reported in CHCV patients with liver cirrhosis, while the CC-genotype was the least common in those with cirrhosis." (PMID 37928048, 2023).
asthma (6 papers, 2014 to 2020). "Indeed, in children with asthma, it was observed that those patients with a minor allele genotype had lower IFNL3 levels in BAL samples, but also significantly higher eosinophil granulocytes in sputa samples with higher Th2 cytokines." (PMID 26038748, 2014). "Thus far there is no literature regarding basal serum IFNL3 levels in asthma patients compared to controls." (PMID 29562888, 2018).
AIDS (4 papers, 2013 to 2019). A syndrome resulting from the acquired deficiency of cellular immunity caused by the human immunodeficiency virus (HIV). "Interestingly, the IFNL3/4 region is also associated with AIDS-related CMV retinitis susceptibility in HIV-infected patients." (PMID 31396258, 2019).
dyslipidemia (2 papers, 2013 to 2022). "After excluding people with abnormal levels of FPG or HbA1C, the associations between IFNL3 polymorphisms with dyslipidemia became even stronger (OR = 5.56, 95%CI, 1.75–16.67, P = 0.001)." (PMID 35784542, 2022). "With regard to the rs12971396 polymorphism of IFNL3, the C allele was the major allele in the non-dyslipidemia and dyslipidemia groups (88% and 96%, respectively)." (PMID 35784542, 2022). "For IFNL3 rs12971396, people with the homozygous genotype (the major group) carried a higher risk of dyslipidemia than people with the heterozygous genotype (P < 0.001, OR = 4.46, 95%CI, 1.95–10.22)." (PMID 35784542, 2022). "Upon comparison of allelic frequencies with P < 0.05 (two-sided) and frequency of the IFNL3 rs12971396 C-allele of 88% in the non-dyslipidemia group and 96% in the dyslipidemia group, the power to detect an association between rs12971396 polymorphism and dyslipidemia reached 91.5%." (PMID 35784542, 2022). "The proportion of the IFNL3 rs12971396 CC genotype was significantly higher in the dyslipidemia group, whereas the CG genotype had a lower proportion." (PMID 35784542, 2022). "The major genotype of IFNL3, which can upregulate the IFLN3 expression (proved by previous research), could be a risk factor of dyslipidemia." (PMID 35784542, 2022). "Polymorphisms of IFNL3 (rs12971396, rs4803219, rs8099917, rs11882871, rs12979860, rs4803217) varied between the non-dyslipidemia group and dyslipidemia group (P < 0.05)." (PMID 35784542, 2022).
lupus nephritis (2 papers, 2019 to 2023). Glomerulonephritis in the context of systemic lupus erythematosus. "Notably, elevated serum levels of IFN-λ3 are significantly correlated with higher SLE disease activity and decreased complement level, and genetically, the IFNL3/4 SNP alleles that contain dysfunctional IFNL4 in combination with low production of IFN-λ3 seem to be risk factors for lupus nephritis." (PMID 31450787, 2019).
myeloproliferative neoplasm (2 papers, 2021 to 2023). A clonal hematopoietic stem cell disorder, characterized by proliferation in the bone marrow of one or more of the myeloid (i.e., granulocytic, erythroid, megakaryocytic, and mast cell) lineages. "A study on myeloproliferative neoplasms (MPN) revealed that the CC genotype of IFNL3 rs12979860 was significantly associated with hematologic response to interferon‐α treatment, with a significantly higher complete response rate compared with non‐CC." (PMID 37329186, 2023).
ZIKV infection (2 papers, 2022 to 2023). "After ZIKV infection, essential antiviral ISGs, such as IFITs and IFITMs, and essential antiviral IFNs, such as IFNL1 and IFNL3, were greatly activated in hTSCs." (PMID 37684223, 2023). "Upon ZIKV infection, the expressions of IFN-related genes (such as IFNL1 and IFNL3) and ISG-related genes (such as ISG15 and ISG20) were only marginally elevated until 24 h.p.i." (PMID 36209057, 2022). "Differently, ZIKV infection tended to up-regulate IFNL3 with FC value of 351-fold in the JEG-3 cell line but up-regulated IFNL1 with FC value of 102.6-fold in U-251 MG cells, indicating IFNL3 in the placenta may be more sensitive for antiviral effects." (PMID 36209057, 2022).
Anxiety (1 paper, 2022). Intense feelings of nervousness, tension, or panic often arise in response to interpersonal stresses. "We searched the microbe-associated genes (IFNL3 and SERPINA5) to explore whether they interacted with miRNAs that were reported with depression/anxiety and microbiota." (PMID 36699448, 2022). "SERPINA5 showed a target of mmu-miR-3095-3p, which was reported to be associated with anxiety-like behavior and microbiota, while IFNL3 was not." (PMID 36699448, 2022).
Arthritis (1 paper, 2018). Inflammation of a joint. "However, IFNL3/4 SNPs were not significant associated with other manifestations such as arthritis, malar rash, leukopenia, positivity of anti-dsDNA/anti-RNP autoantibodies, and depressed complement levels among SLE patients (data not shown)." (PMID 30157968, 2018).
cholestasis (1 paper, 2021). Impairment of the bile flow caused by obstruction within the liver, or outside the liver in the bile duct system. "There was a negative correlation between TLR3 and IFNL3 and the serum levels of GGT, suggesting that these two markers can efficiently suppress virus replication and influence the levels of one of the main characteristics of HCV infection: cholestasis (blockage of the bile ducts)." (PMID 34207750, 2021).
CMV retinitis (1 paper, 2019). "In a large Swiss HIV Cohort Study, the effect of IFNL3 TT/-G substitution, the variant that increased susceptibility to CMV replication in transplant patients, was also shown to be associated with higher risk of CMV retinitis." (PMID 31396258, 2019).
lung adenocarcinoma (1 paper, 2015). A carcinoma that arises from the lung and is characterized by the presence of malignant glandular epithelial cells. "We used human A549 lung adenocarcinoma cells for these experiments because they express IFNL3 mRNA upon transfection with poly(I:C)." (PMID 26531896, 2015).
malaria (1 paper, 2021). Malaria is a serious and sometimes fatal disease caused by a parasite that commonly infects a certain type of mosquito which feeds on humans. "In a cohort of 914 Malian children, we genotyped functional variants IFNL4-rs368234815, IFNL4-rs117648444, and IFNL3-rs4803217 and analyzed episodes of malaria, gastrointestinal, and respiratory infections recorded at 30,626 clinic visits from birth up to 5 years of age." (PMID 33850301, 2021).
mastitis (1 paper, 2020). Inflammation of breast tissue during lactation or postpartum due to an obstructed duct or infection. "Five genes (EPOR, IL9, IFNL3, CCL26, and IL26) that were involved in this pathway might serve as potential molecular markers for breeding programs that enhance resistance to S. aureus infection and mastitis." (PMID 32944235, 2020).
nephritis (1 paper, 2018). Inflammation of renal tissue. "In contrast, the major alleles of IFNL3/4 SNPs are a significant risk factor for the development of nephritis among SLE patients." (PMID 30157968, 2018). "Subsequently, we used haplotype analysis to determine whether IFNL3/4 SNP haplotypes (rs8099917, ss469415590, rs12979860, and rs4803217) are associated with the risk for nephritis among SLE patients." (PMID 30157968, 2018). "Since IFNL3/4 SNP haplotypes were associated with lupus nephritis, we carried out immunohistochemistry analyses to examine the presence of IFNL and its receptor in kidney tissues of three SLE patients with nephritis." (PMID 30157968, 2018). "Indeed, we have detected both IFN-λ3 (IFNL3) and IL-28 receptor alpha in kidney tissue, suggesting a pathogenic mechanism of IFN-λ3 in the development of SLE nephritis." (PMID 30157968, 2018). "Specifically, minor alleles of all IFNL3/4 SNPs are risk factors for SLE development in patients without nephritis." (PMID 30157968, 2018). "We found that the most common IFNL3/4 SNP haplotype containing the rs4803217C allele was significantly associated with the low risk for SLE in nephritis-negative patients, confirming that a high producer of IFN-λ3 may have a protective role against SLE." (PMID 30157968, 2018). "B IFNL3 levels not significantly different (unpaired t test t = 1.650, P = 0.103) between nephritis-positive patients (N = 40; IFNL3 concentration 4.645 ± 1.039 pg/ml) and nephritis-negative patients (N = 40; IFNL3 concentration 7.065 ± 1.036 pg/ml)." (PMID 30157968, 2018). "However, IFNL3 levels were not significantly different (unpaired t test t = 1.650, P = 0.103) between nephritis-positive patients and nephritis-negative patients." (PMID 30157968, 2018).
Sepsis (1 paper, 2020). Sepsis is defined as life-threatening organ dysfunction caused by a dysregulated host response to infection. "However, this hypothesis must be confirmed by further studies covering the analysis of serum levels of cytokines, gene expression products, and IFNL3 polymorphisms in patients with sepsis." (PMID 32478085, 2020). "However, the association of IFNL3 SNPs with the dysregulated inflammatory response in patients with sepsis has not been reported so far." (PMID 32478085, 2020).
tick-borne encephalitis (1 paper, 2017). Tick-borne encephalitis is caused by an arbovirus of the Flaviviridae family (tick-borne encephalitis virus, TBEV), transmitted principally by the bite of the Ixodes ricinus tick. "It has been shown in the Russian population that five SNPs in OAS2 and OAS3 genes, as well as two SNPs in IFNL3/IL28B gene and polymorphisms in the TLR3, CD209, and IL10 genes were associated with predisposition to severe forms of tick-borne encephalitis." (PMID 29297316, 2017).
ulcer (1 paper, 2021). "Transcriptional analysis of biopsy tissue indicated that type II interferon, IFNG, not type I (IFNA4 and IFNB1) nor type III (IFNL1, IFNL2, IFNL3) interferons, was the prevalent interferon gene detected in ulcer lesions and 8 weeks post-healed skin." (PMID 34552595, 2021).